MIP (major intrinsic protein of lens fiber)
Description:
Aquaporins form homotetrameric transmembrane channels, with each monomer independently mediating water transport across the plasma membrane along its osmotic gradient. Specifically expressed in lens fiber cells, this aquaporin is crucial for maintaining lens water homeostasis and transparency. Beyond water permeability, it also acts as a cell-to-cell adhesion molecule, forming thin junctions between lens fiber cells that are essential for maintaining the ordered structure and transparency of the lens.
Synonyms: MP26; AQP0; LIM1; CTRCT15; MIP26
Tractability: Antibody: UniProt places it where antibodies can reach, with high confidence; its Gene Ontology location is reachable by antibodies, with high confidence; UniProt predicts a signal peptide or a membrane-spanning region.
Gene: Protein-coding gene on chromosome 12 (56,449,502 to 56,469,166, reverse strand). Ensembl gene ENSG00000135517.
Subcellular location: Cell membrane; Cell junction
Pathways (Reactome):
Transport of small molecules: Passive transport by Aquaporins
Gene Ontology:
Molecular function: cell adhesion mediator activity; protein binding; water channel activity; calmodulin binding; channel activity; structural constituent of eye lens
Biological process: gap junction-mediated intercellular transport; homotypic cell-cell adhesion; maintenance of lens transparency; water transport; canalicular bile acid transport; transmembrane transport
Cellular component: plasma membrane; anchoring junction; apical plasma membrane; intracellular canaliculus; membrane
Genetic constraint (gnomAD): Loss-of-function variants: 11 observed, 19.33 expected, observed/expected ratio (o/e) 0.57, 90% interval 0.36 to 0.94. The upper end of that interval is the gene's LOEUF score, 0.94, which puts it in group 3 of 6, group 1 being the genes least tolerant of losing a copy. Missense variants: 221 observed, 311.57 expected, observed/expected ratio (o/e) 0.71, 90% interval 0.63 to 0.79. Synonymous variants: 123 observed, 137.61 expected, observed/expected ratio (o/e) 0.89, 90% interval 0.77 to 1.04.
Homologues: Orthologues: chimpanzee MIP (100% identical), macaque MIP (97% identical), dog MIP (94% identical), guinea pig MIP (94% identical), rat Mip (94% identical), mouse Mip (93% identical), rabbit MIP (93% identical), pig MIP (93% identical), tropical clawed frog mip (77% identical), zebrafish mipa (70% identical), zebrafish mipb (66% identical), Drosophila melanogaster Eglp4 (29% identical), and 3 more. Paralogues in human: AQP2 (61% identical), AQP5 (53% identical), AQP6 (51% identical), AQP1 (45% identical), AQP4 (43% identical), AQP7 (29% identical), AQP8 (28% identical), AQP7B (27% identical), AQP3 (26% identical), AQP9 (25% identical), AQP10 (24% identical).
Diseases named in the same sentence as MIP in open-access papers:
MIP is named in the same sentence as 79 diseases in open-access papers, as found by Europe PMC text mining. Sharing a sentence is not in itself a finding about the gene and the disease. The quoted sentences say what the papers report.
cataract (35 papers, 2008 to 2023). Partial or complete opacity of the crystalline lens of one or both eyes that decreases visual acuity and eventually results in blindness. "We screened 11 genes often associated with human cataracts and identified a novel missense mutation (c.686G > A) in the MIP gene encoding major intrinsic protein." (PMID 33530927, 2021). "At least 19 mutations in the human MIP gene have been linked to autosomal dominant cataracts with diverse phenotypes, reflecting the multi-domain and multi-functional nature of the protein." (PMID 33530927, 2021). "For example, mutations in the major intrinsic protein (MIP, also known as aquaporin 0) promote cataract formation in human infants, and several strains of rats and mice with loss-of-function mip mutations also develop fully penetrant cataracts." (PMID 34706646, 2021). "We screened 11 genes often associated with human cataracts and identified a novel missense mutation (c.686G > A) in the MIP gene in a female panda diagnosed with progressive cortical punctate cataracts by using a functional candidate gene screening approach." (PMID 33530927, 2021). "Four of these—coding variants in GCK with diabetes mellitus, LoF variants in HBB with hemoglobinopathies, LoF variants in PKD1 with cystic kidney disease, and coding variants in MIP with cataracts—are novel conditions for population screening." (PMID 34385667, 2021). "While previous studies have implicated MIP variants in rare, familial, congenital cataracts, our results provide evidence for a more general role of MIP in cataracts." (PMID 34385667, 2021). "The first mutation in H6 of MIP (C.638delG) was reported to be associated with polymorphic cataracts in 2006, and the second mutation of MIP (IVS-1G>A) was found to be associated with nuclear “snail-like” cataracts in 2009." (PMID 25033405, 2014). "The phenotypes of cataracts are significantly different among MIP mutation families, pointing to the presence of extensive clinical heterogeneity of hereditary cataracts." (PMID 24405844, 2014). "And a novel nonsense mutation in MIP that co-segregated with the disease was identified to be responsible for the congenital cataracts." (PMID 24405844, 2014). "To date, several mutations in human MIP, including missense and frameshift mutations,have been reported to induce inherited cataracts." (PMID 24405844, 2014). "It has been widely reported that mutations of MIP in humans and mice are involved in the induction of cataracts." (PMID 25033405, 2014). "In particular, it is known that cataracts caused by different types of mutant MIP have different phenotypes, suggesting that Mip mutations cause phenotypic heterogeneity." (PMID 23226368, 2012). "Mutations in both PITX3 and MIP/AQP0 are implicated in congenital cataracts in humans and result in lens phenotypes in mice." (PMID 21698120, 2011). "All the MIP mutations including p.R187C identified in this study present bilateral cataracts as the autosomal dominant phenotype, indicating the important structural role of MIP in the lens." (PMID 21245956, 2011). "This study has identified a novel MIP mutation, p.V107I in a Chinese family with congenital cataracts." (PMID 20361015, 2010). "To date, several mutations in human MIP have been identified, most of which are missense mutations.The cataracts induced by MIP mutation are usually located in the lens nuclear region." (PMID 20361015, 2010). "Here we identified the first MIP mutation associated with cataracts in the giant panda." (PMID 33530927, 2021). "Currently, 12 mutations in MIP have been linked to autosomal-dominant cataracts in humans." (PMID 33204712, 2020). "The results add to the list of mutations of the MIP linked to cataracts." (PMID 24405844, 2014). "Mutations in the human MIP/AQP0 gene were shown to underlie various dominant forms of cataracts." (PMID 21698120, 2011).
cataract (continued). "Therefore, our data suggest that PITX3 is involved in direct regulation of MIP/AQP0 expression and that the alteration of MIP/AQP0 expression is likely to contribute to the lens phenotype in cataract patients with PITX3 mutations." (PMID 21698120, 2011). "The cataracts caused by MIP mutation are usually located in the nuclear region of the lens." (PMID 21245956, 2011). "These subtle changes in the surface properties and intramolecular interactions are likely to influence the behavior of the C-terminal tail of panda MIP and thus promote the formation of cataracts." (PMID 33530927, 2021). "Loss of MIP function results in a syndrome which consists of LVNC, DD, seizures, hypotonia, and cataracts." (PMID 27799064, 2016). "All family members with the G215D mutant of MIP have punctate cataracts, and the opacity degree of the lens increases with increasing age." (PMID 25033405, 2014). "The diverse cataract phenotypes caused by the same MIP gene suggests that other genetic modifiers are likely to influence the expression and function of AQP0 in lens development and Y suture formation." (PMID 20361015, 2010). "It is interesting to note that recessive mutations in the human MIP gene cause a wide variety of syndromes including left ventricular non-compaction, development delay, hypotonia, seizures, cataracts, and early childhood death." (PMID 33669127, 2021). "Although mutations affecting MIP have been shown to cause cataracts in humans and mice, analogous mutations have not been reported in the giant panda (Ailuropoda melanoleuca)." (PMID 33530927, 2021). "Moreover, common mutations associated with cataracts of various morphologies include genes encoding crystallins (CRYA, CRYB, and CRYG), lens specific connexins (Cx43, Cx46, and Cx50), major intrinsic protein (MIP) or aquaporin, heat shock transcription factor 4 (HSF4), etc. but PAX6 is neglected." (PMID 36843716, 2023). "However, this does not restore the ordered packing of the lens fiber cells and still results in the formation of cataracts, confirming that MIP has unique functions in the lens that are not complemented by other aquaporins." (PMID 33530927, 2021). "Immunostaining for E-cadherin (epithelial cells), and MIP (lens fiber cells) in WT and bs2 lenses prior to the onset of cataracts did not identify any difference between WT and bs2 mice at P14 (not shown), indicating that lens epithelial cells were undergoing normal development and differentiation." (PMID 25197626, 2014).
malaria (22 papers, 2009 to 2026). Malaria is a serious and sometimes fatal disease caused by a parasite that commonly infects a certain type of mosquito which feeds on humans. "In Madhya Pradesh, Pf was the main MiP-associated malaria species on ANC visits and DU with overall peripheral Pf mono-infections prevalence of 3.4–48.5% based on LM." (PMID 37927870, 2023). "Several studies have suggested immune tolerance as one of the potential mechanisms for the observed association between MiP and the risk of malaria in infants." (PMID 31481075, 2019). "Only two studies have investigated the relation between MiP and infant growth and found that placental or peripheral malaria at delivery was independently associated with lower weight at 12 months." (PMID 26879849, 2016). "Decreased levels of peripheral and placental Ang-1 have previously been associated with the occurrence of malaria in pregnancy in African women, in an area of high P. falciparum transmission and where the detrimental effects of MiP are substantial." (PMID 26090803, 2015). "In line with previous reports of gravidity-dependent susceptibility to MIP in malaria endemic regions, the risk of P. falciparum infection was highest in primigravidae and the proportion of submicroscopic parasitaemia among infected women decreased with increasing gravidity." (PMID 36178962, 2022). "In addition to its well-known effects on maternal anemia and low birthweight, MiP has been associated with an enhanced susceptibility to malaria as well as to other infections in infancy." (PMID 31536589, 2019). "However, studies evaluating the association between MiP and malaria in infancy have shown mixed results." (PMID 31481075, 2019). "Further research is needed to confirm or exclude an association between MiP and malaria in infancy." (PMID 31481075, 2019). "This study also underlines how when designing MiP prevention and control strategies, in addition to the changing contexts of malaria transmission and drug resistance, it is necessary to take into account the specific and fluid local relationships between malaria and illness during pregnancy." (PMID 23876079, 2013). "PM vaccine candidates targeting the VAR2CSA antigen (PRIMVAC and PAMVAC) are in development, and existing malaria vaccines preventing infection are being repurposed to prevent MiP." (PMID 41887022, 2026). "As existing malaria control strategies remain insufficient, MiP vaccines have the potential to complement them by eliciting immunity comparable to that seen in multigravidae." (PMID 41887022, 2026). "One study reported an apparent reduction in Pf MiP burden from ~60 to 5% during years 1994–2019 in different malaria eco-epidemiological regions (coastal savannah zone, middle forest zone, and northern savannah zone) in Ghana." (PMID 37927870, 2023). "Although other candidate therapies, such as dihydroartemisinin-piperaquine, are still being investigated, and despite waning SP efficacy due to increasing parasite resistance, SP remains an essential component of MiP prevention in malaria-endemic areas." (PMID 37090061, 2023). "Most of the IgGs analysed are known markers of malaria exposure (like IgG to PfAMA-1) or MiP (like IgG to PfDBL5e or PfDBL3x)." (PMID 36380370, 2022). "While Tororo, Uganda is considered a high-transmission region for malaria, the prevalence of malaria in this study cohort was relatively low; however, women are still showing MIP-induced changes in inflammatory profiles." (PMID 31043691, 2019). "The elevated concentrations of sTNFR2, sICAM-1, and IL-18BP we observed in association with MiP in WLHIV, indicate a malaria-induced systemic inflammatory response." (PMID 31043691, 2019). "Further studies in southern Laos are needed to draw a more representative picture of MiP, including both asymptomatic and sub-microscopic Plasmodium infections that have deleterious consequences during pregnancy and contribute to malaria transmission." (PMID 27566274, 2016).
malaria (continued). "Even though estimates in the literature had a wider range, MiP prevalence was limited to between 2% and 14% as it is assumed that values above or below these values will be inconsistent with the current level of malaria transmission in Madhya Pradesh." (PMID 19210797, 2009). "Moreover, the dose–response relationship that we observe between malaria and LBW further strengthens the posited causal association between MiP and birth-weight." (PMID 36650337, 2023). "Therefore, MiP is a useful marker for malaria surveillance as recommended by the WHO as this helps the country to evaluate the impact of malaria control programs as well as to revise or reinforce already existing intervention strategies." (PMID 37824491, 2023). "Meanwhile, considering the high prevalence of MiP among pregnant women in this age category (18.5%), the hemolytic effect of malaria could be blamed for the predominant AiP prevalence observed among this age group." (PMID 35877761, 2022). "Improved knowledge as to how the yolk sac responds to MiP may improve the understanding of the mechanisms by which malaria impacts pregnancy outcome." (PMID 32779889, 2020). "In the present study, we hypothesized that MiP, in a murine model of malaria‐induced IUGR and PTL, modifies the yolk sac morphology and efflux transport potential, via modulation of key ABC efflux transporters." (PMID 32779889, 2020). "We did not evidence any association between MiP or malaria-schistosomiasis coinfection and infant’s Hb concentration." (PMID 31536589, 2019). "Investigating the possibility of congenital malaria in murine models of MiP." (PMID 31275284, 2019). "This study shows that despite frequent active screening and prompt treatment of MiP, impaired growth and an increased risk of malaria and non-malaria infections can be observed in the infants." (PMID 26879849, 2016). "Nevertheless, given the lack of association between LBW and local malaria concepts, it does not seem to affect acceptance of MiP treatment or prevention." (PMID 23876079, 2013). "Meanwhile, being positive for MiP posed a 12.10 times risk (95% CI:1.35–85.06; p = 0.025) of AiP compared to those negative for malaria whereas failure to attend ANC as scheduled posed 6.34 times risk (95% CI:1.81–22.19; p = 0.004) of AiP among the pregnant women studied." (PMID 35877761, 2022). "Changes in ABCA1 and P‐gp in MiP may alter the biodistribution of toxic substances, xenobiotics, nutrients and immunological factors within the fetal compartment and participate in the pathogenesis of malaria‐induced IUGR and PTL." (PMID 32779889, 2020). "Indeed, the association between MiP, particularly placental malaria, and a higher risk of infant’s malaria and non-malaria fever during the first 18 months of life has already been reported." (PMID 31536589, 2019). "Using a prospective longitudinal cohort study of malaria-exposed pregnant women from PNG, we investigated antibody-complement interactions in immunity to MiP." (PMID 34425801, 2021). "To examine the impact of MiP in WLHIV on systemic inflammation we quantified longitudinal changes in inflammatory proteins by gestational age and malaria status." (PMID 31043691, 2019). "Rather then segregating the women into MiP positive or negative, thus reducing the power of our analysis, we investigated whether these associations were modified by the presence or absence of malaria during pregnancy by adding Plasmodium spp." (PMID 26090803, 2015). "Despite the decrease of malaria cases during the evaluation period and regardless of Plasmodium species, we present evidence of the deleterious effects of MiP in a low transmission area in the Amazonian region." (PMID 29928025, 2018).
malaria (continued). "Eotaxin-2 concentrations show an opposite pattern to eotaxin-1 in MiP, with increased levels in pregnant compared to non-pregnant malaria-exposed groups, increased placental levels compared to periphery, and enhanced placental concentrations in the malaria-exposed than in the malaria-naive women." (PMID 36380370, 2022).
congenital cataracts (16 papers, 2008 to 2024). "Although some main intrinsic protein (MIP) mutations linked to congenital cataracts have been identified in mice and humans, the heterogeneous phenotypes observed imply an intricate mechanism for MIP function." (PMID 29695758, 2018). "The importance of MIP and connexins is exemplified by the number of mutations found in these genes in mouse and human that result in congenital cataracts." (PMID 25406393, 2014). "To date, several mutations in MIP have been linked to mouse and human congenital cataracts." (PMID 28059152, 2017). "There were no pathological mutations in known genes associated with non-syndromic congenital cataracts, like CRYB, CRYG, Cx43, Cx46, Cx50, MIP, PITX3, MAF, HSF4, and so on." (PMID 28076398, 2017). "For example, a mutation in CRYBB2 and CRYGD can cause CCA; in addition, MIP (also known as AQP0), CRYBA1, and GJA3 are related to congenital cataracts with punctate opacities." (PMID 25033405, 2014). "Furthermore, mutations in the major intrinsic protein (MIP, also known as AQP0) have been linked to congenital cataracts." (PMID 37762642, 2023). "At least 19 mutations in the human MIP gene are associated with congenital cataracts, 11 of which are missense mutations, as well as two nonsense mutations, two frameshifts, two splice-site mutations, and one initiation codon mutation." (PMID 33530927, 2021). "Congenital cataracts are typically caused by mutations in genes encoding lens regulatory (e.g. FOXE3, HSF4, MAF, PAX6 and PITX3) and structural (e.g. crystallins, connexins, MIP, BFSP2, EPHA2, EPHA5 and LIM2) proteins." (PMID 25406393, 2014). "Mutations in MIP have been linked to mouse and human congenital cataracts, but there was no report about the association between the single nucleotide polymorphisms (SNPs) in MIP and ARC until now." (PMID 21921980, 2011).